INS (insulin)
Diseases named in the same sentence as INS in open-access papers (continued):
Sharing a sentence is not in itself a finding about the gene and the disease.
Insulin resistance (continued). "In addition, long-time treatment with Compound B reduced plasma glucose levels and tended to reduce insulin concentrations, suggesting that Compound B would improve insulin resistance." (PMID 25405858, 2014). "Insulin-resistance plays a significant role in both obesity and prediabetes (Reaven 1988, Ferrannini 1993) and the reversal of the insulin-resistant state could prevent the development of several metabolic diseases." (PMID 24204009, 2014). "Moreover, evidence suggests that loss of β-cell function in T2D patients is the major determinant of disease progression compared to insulin resistance which leads to initiation of oral glucose lowering polypharmacy and subsequent use of insulin." (PMID 25157406, 2014). "However, the degree of increase of insulin secretory function required to overcome insulin resistance would differ according to various glucose tolerance status." (PMID 24586809, 2014). "This hypothesis was supported by initial experiments, which showed that treating cells with Go-6976 partially prevented the development of insulin resistance in cells, which had been pretreated with high glucose and low dose insulin." (PMID 25330241, 2014). "Incapability of generating endothelial NO and reduced blood flow to skeletal muscle and peripheral tissues deteriorate insulin action and glucose uptake by the cells and may lead to insulin resistance." (PMID 26109894, 2014). "In addition, the changes in waist and hip circumference, FBS, plasma insulin and insulin resistance had significant interaction with the time between the groups." (PMID 25560330, 2014). "Several independent observations have shown a relationship between low birth weight and insulin resistance; reduced insulin sensitivity might be secondary to altered programming of metabolic pathways in presence of adverse intrauterine environment." (PMID 25045669, 2014). "Thus therapeutic agents that ameliorate insulin resistance or stimulate the secretion of insulin and several kinds of insulin preparations for direct injection have received considerable attention." (PMID 24551069, 2014). "In overweight PCOS women, insulin resistance is certainly associated with increased steroidogenesis, even if the adipose cell lineage is not intrinsically insulin-resistant." (PMID 24895638, 2014). "This may because adipose tissues plays an important role in the regulation of insulin sensitivity through secreting adipocytokines, which are involved in the pathogenesis of pregnancy-induced insulin resistance." (PMID 24498216, 2014). "If so, insulin resistance would worsen as the level of circulating insulin increases during compensation, which could contribute to the transition of insulin resistance to more severe disease." (PMID 25259572, 2014). "We found that fasting blood glucose, fasting plasma insulin, and insulin resistance which were evaluated by the cumulative changes in blood glucose responses quantified by the incremental area under the curve in IPGTT test were significantly increased in HFD-fed mice." (PMID 24991305, 2014). "In UT-HET3 mice, eRAPA impaired glucose tolerance and caused insulin resistance in combination with both low fat and high fat diets but did not affect fasting glucose or insulin levels." (PMID 25324470, 2014). "Consequently, higher sUA always keeps with more severe insulin resistance, that is, greater insulin demand of our organs." (PMID 24971368, 2014). "First, insulin resistance induced by excess insulin observed in this study occurred mainly in liver as evidenced by the increased level of serine-phosphorylated IRS1 and lack of Akt phosphorylation in response to acute insulin challenge in liver but not in muscle." (PMID 24741073, 2014).
Insulin resistance (continued). "While peripheral insulin resistance is common during obesity and aging in mice and humans, its progression to T2D is largely due to insulin secretory dysfunction and significant apoptosis of functional β-cells, leading to an inability to compensate for insulin resistance." (PMID 25147566, 2014). "Therefore, we treated insulin-resistant HepG2 cell with 2.5, 5.0, or 10 μm of compound 6 to assess its effects on 6 HK and PK activities and insulin resistance." (PMID 24918297, 2014). "Besides, UA treatment significantly alleviated HFD-induced insulin resistance by lowering insulin level and improving insulin resistance index (HOMA-IR), and decreasing leptin and elevating adiponectin levels in serum." (PMID 24489777, 2014). "Moreover, intraperitoneal or intracerebroventricular administration of bromocriptine, a potent dopamine D2 receptor agonist, to seasonal insulin resistant animals reverses the insulin resistance/glucose intolerance." (PMID 25937836, 2014). "Thus, it seems that increased concentration of FFAs following infusion of LE had a dual influence on blood glucose concentrations, first by decreasing insulin secretion from pancreas and second by inducing a state of insulin resistance." (PMID 25568690, 2014). "Moreover, obesity per se, was also accompanied by elevated cholesterol, insulin, and insulin resistance levels, and leptinaemia." (PMID 24466104, 2014). "Nevertheless, these authors suggest that the proportion of the circulating visfatin and insulin molecules, expressed as the visfatin/insulin ratio, more than visfatin alone would be a good indicator for prevention of the development of insulin resistance and MetS in the obese." (PMID 24741591, 2014). "Therefore, hyperinsulinemia can be an important factor in hypertension associated with metabolic syndrome, if the stimulatory effects of insulin on renal sodium absorption are preserved even in the systemic insulin resistance." (PMID 24982885, 2014). "Additionally, studies in animal models of insulin resistance indicate that resveratrol increases insulin function." (PMID 24734227, 2014). "Type 1 DM, previously called insulin dependent, usually develops in childhood and adolescence as a result of impairment of pancreatic islets β-cells, whereas type 2 DM results from insulin resistance—an inappropriate response of body tissue to insulin—and usually develops in adulthood." (PMID 23820625, 2014). "One is the failure of insulin secretion by pancreatic β-cells and the other is insulin resistance." (PMID 24705496, 2014). "Type 2 diabetes is characterized by increased insulin resistance and impaired insulin secretion." (PMID 24692847, 2014). "An improved understanding of that memory may help define interventions to reset the IR to full insulin responsiveness and impede the progression of insulin resistance to more severe disease states." (PMID 25259572, 2014). "However, adipose tissue is metabolically active with multiple endocrine and immune functions, with the potential to produce disturbances in insulin signaling pathways resulting in increased insulin resistance with increasing weight." (PMID 25368857, 2014). "The analysis of our study revealed head fat was correlated positively with fasting insulin and fasting C peptide in females, suggesting head fat deposit might be a key feature of hyperinsulinemia and insulin resistance." (PMID 25015267, 2014). "PKC induce insulin resistance by inhibiting insulin-stimulated phosphorylation of IRS proteins." (PMID 25486190, 2014). "Although HOMA-IR has been shown to have a good relationship with the hyperinsulinemic euglycemic clamp technique, a more accurate method for assessing insulin resistance, such as the oral glucose tolerance test or the glycemic insulin clamp test, should be used in future studies." (PMID 25551248, 2014).
Insulin resistance (continued). "In this paper, we report a patient with type 1 diabetes with a form of immune-mediated insulin resistance, in which the insulin resistance has been developed as a result of the presence of circulating insulin antibodies, with possible tissue resistance to subcutaneous insulin." (PMID 24711924, 2014). "Current smoking status in the normoglycaemic group was associated with lower insulin sensitivity and higher insulin resistance compared to those who had never smoked or were previous smokers." (PMID 24416185, 2014). "In this context, it was demonstrated that treatment with insulin sensitizers (e.g., liragultide, pioglitazone) ameliorates central insulin resistance, improves cognitive impairment, enhances synaptic plasticity, and significantly decreases levels of Tau phosphorylation in the rat brain." (PMID 24574966, 2014). "In fact, from a metabolic standpoint, elevated NEFA concentration is established as one of the main contributing factors for the development of insulin resistance through the impairment of both hepatic glucose production and insulin action in peripheral tissues." (PMID 25371817, 2014). "Hospitalized patients often require high insulin doses to achieve target glucose levels because of increased insulin resistance; thus, in addition to basal and nutritional insulin requirements, patients often require supplemental or correction insulin for the treatment." (PMID 25097540, 2014). "Insulin resistance, “a relative impairment in the ability of insulin to exert its effects on glucose, protein and lipid metabolism in target tissues,” has many detrimental effects on metabolism and is strongly correlated to deposition of lipids in non-adipose tissues." (PMID 25601841, 2014). "It appears that it contributes both to insulin-sensitization and insulin-resistance." (PMID 24809394, 2014). "The gold-standard method for quantitating the degree of insulin resistance (i.e., the euglycemic-hyperinsulinemic clamp procedure) was discussed to provide a background for the correct assessment of insulin secretion in patients with prediabetes and T2DM under various therapies." (PMID 24524730, 2014). "Circulating cytokines have been shown to negatively affect the insulin signaling pathway and may contribute to insulin resistance." (PMID 25347855, 2014). "In our study, both SOCS3 and PKCε were significantly increased with the development of NAFLD, which was consistent with the impairment of insulin signaling pathway, indicating these regulatory molecules may contribute to the insulin resistance." (PMID 25160038, 2014). "Interestingly, this study shows additional features of these indices as predictors of insulin resistance and - to less extent - insulin secretion." (PMID 24732091, 2014). "Fructose may also indirectly increase serum levels of uric acid by increasing insulin resistance, leading to impaired glucose tolerance, and elevated circulating insulin levels." (PMID 24884821, 2014). "As hyperinsulinemia may drive obesity and insulin resistance, we examined whether defects in β-cell mass or function could contribute to the low insulin levels in WSB mice." (PMID 24505481, 2014). "Additionally acute phase proteins and certain cytokines are related with and through a great number of metabolic pathways that regulate insulin, the functions of lipoproteins lipases, and adipocytes, contributing to the development of insulin resistance." (PMID 24741627, 2014). "However, it has also been described that gonadotropin releasing hormone analogues can alter serum lipoprotein levels and can increase insulin resistance, potentially deteriorating the insulin resistant state in many obese women." (PMID 24498875, 2014). "Alternatively, insulin resistance could also result from the decreased levels of nitrated insulin signaling molecules via proteolytic degradation, usually observed at later time points following exposure to persistent insults." (PMID 24876909, 2014).
Insulin resistance (continued). "T2DM is sustained by insulin resistance and impaired insulin secretion." (PMID 25347846, 2014). "Insulin resistance is typically present for some years before diagnosis, manifested as diminished stimulation of glucose transport in muscle and adipose tissue and inadequate suppression of glucose production in the liver in response to insulin." (PMID 26171320, 2014). "Consequently, an impaired microvascular insulin response due to endothelial dysfunction has been suggested to contribute to the development of insulin resistance; Clark 2008)." (PMID 24744873, 2014). "Impaired insulin signaling either by altered levels of fatty acids in DM and related metabolic syndrome or pro-inflammatory cytokines (IL6 and TNF-α) that accumulate during insulin resistance is implicated in podocyte injury." (PMID 25309512, 2014). "Insulin resistance is a complex pathophysiological feature with different organs and targets in the carbohydrate metabolism that can be genetically influenced; in this setting our study reinforces ESR1 Xbal polymorphism as a piece in insulin sensitivity." (PMID 25077953, 2014). "Furthermore, current evidence suggests that the administration of exogenous TNF-alpha to animals can induce insulin resistance, whereas its neutralization can improve insulin sensitivity." (PMID 24991532, 2014). "One proposed mechanism linking obesity, insulin resistance, and T2D suggests that a defect in the ability of β-cells to secrete insulin is sufficient to lead to decreased insulin signaling in the hypothalamus, resulting in increased food intake and thus weight gain." (PMID 25337808, 2014). "Impairment of GLUT4 expression, GLUT4 translocation, and/or insulin signaling may affect insulin-stimulated glucose uptake, and that would result in insulin resistance and hyperglycemia." (PMID 24550994, 2014). "Moreover, all the HOMA parameters i.e, beta cell function (%B), insulin sensitivity (%S) and insulin resistance (IR) were found to be statistically significantly different between groups [p<0.001]." (PMID 24416185, 2014). "Although sexual and racial differences might influence the associations between insulin resistance and TG, as well as TG/HDL-C, many studies have shown that increasing TG and decreasing HDL-C could deteriorate insulin sensitivity." (PMID 25136362, 2014). "Insulin resistance and elevated levels of insulin and IGF are known to induce breast cancer growth." (PMID 25338520, 2014). "Fasting blood sugar, insulin levels and calculated insulin resistance index of HOMA IR." (PMID 24476202, 2014). "Physical exercise exerts ameliorating effects on insulin resistance by increasing mitochondrial formation of ROS in skeletal muscle to induce expression of PGC1α, PGC1β, and PPARγ as inducers of insulin sensitivity as well as SODs 1 and 2 and glutathione peroxidase 1, key enzymes of ROS defense." (PMID 25143800, 2014). "Also, amino acids are reported to directly contribute to insulin resistance by disrupting insulin signaling." (PMID 24971671, 2014). "While normal-weight mice increased locomotor activity in response to intracerebroventricular (i.c.v.)insulin and therefore kept the balance between food intake and energy expenditure, insulin resistance as present in obese mice compromised brain and locomotor activity to lower blood glucose levels." (PMID 24643026, 2014). "Type 2 diabetes is characterized by both insulin resistance and impaired insulin secretion." (PMID 25133699, 2014). "Indeed, palmitoleic acids were shown to increase insulin-stimulated glucose uptake by the skeletal muscles and to reduce liver steatosis, inflammation, and insulin resistance, thus attenuating high-fat diet-induced hepatic glucose production." (PMID 25147439, 2014). "However, as researchers began to explore the potential role of insulin resistance in the pathogenesis of Alzheimer’s disease, it was found that humanin is also a central regulator of peripherial insulin sensitivity." (PMID 25674466, 2014).
Insulin resistance (continued). "Variants in this gene have been associated with type 2 diabetes, insulin resistance, and impaired insulin secretion in non-diabetic subjects." (PMID 25071839, 2014). "These in vivo results implicate that HF islets may compensate for insulin resistance (i.e. progressive hyperinsulinemia), but incompletely (i.e. blunted increase of insulin secretion upon a glucose load)." (PMID 24505268, 2014). "Decreased triglycerides may in turn contribute to the improved insulin signal transduction and reverse insulin resistance of obese mice." (PMID 25115836, 2014). "Furthermore, several studies on the pathogenesis of type 2 diabetes reported that impaired insulin secretion is more prominent than insulin resistance, even in the status of impaired glucose tolerance." (PMID 25530810, 2014). "In T2DM, pancreas produces insulin, but, for reasons that remain unclear, cells are unable to use it, a characteristic of insulin resistance etiology." (PMID 24574966, 2014). "Biological mechanisms whereby high-sugar foods consumption might increase risk of cancer development are related to the development of hyperglycemia, stimulation of insulin production, and insulin resistance." (PMID 24829560, 2014). "On the basis of fasting plasma insulin and glucose levels homeostasis model assessment of insulin resistance (HOMA-IR), two distinct obese subgroup profiles were identified by HOMA-IR z-score, and subdivided in normoinsulinemic obese and hyperinsulinemic obese volunteers." (PMID 24966877, 2014). "Obesity, and in particular insulin resistance, might drive symptoms of reward-based eating, as insulin dampens reward activity and low insulin enhances both reward and opioid activity." (PMID 24979216, 2014). "Because increased SIRT1 expression or activation could improve insulin resistance and enhance insulin secretion through deacetylation and activation of PGC-1a." (PMID 24759758, 2014). "Given that obesity is an important determinant of glycaemic traits and insulin resistance, we assessed the association between the GPS on one hand and fasting plasma glucose, HbA1c and insulin levels, the HOMA-IR and HOMA-B scores and the risk of T2D on the other." (PMID 24885863, 2014). "Of note is the apparent delay between the engagement of sympathetic nerve activity in obesity and the development of insulin resistance suggesting sympathetic overactivity may occur in response to very early changes in plasma insulin." (PMID 25520669, 2014). "Calcineurin inhibitors lower insulin secretion while steroids contribute to insulin resistance." (PMID 24959347, 2014). "This type of eating, with its related rapid spikes of glucose in the blood and subsequent rapid increases in insulin, may contribute to diet-related disorders such as cardiovascular disease and insulin resistance." (PMID 25162598, 2014). "Serum 25(OH)D levels and fasting plasma glucose, insulin, and insulin resistance." (PMID 25072652, 2014). "Moreover, insulin resistance within the β-cells is suggested to aggravate the impaired insulin secretion and contribute to cell damage." (PMID 24896641, 2014). "Moreover, SJW induced insulin resistance and blunted insulin-stimulated glucose uptake in both murine and human adipocytes in vitro." (PMID 25136373, 2014). "Therefore, in T2D, insulin secretion is unable to quickly compensate for insulin resistance, leading to increased postprandial sugar levels and greater elevation of GA (known to be an index reflecting postprandial glycemic status) compared to A1c." (PMID 24586809, 2014). "There are numerous reports indicating that cellular and molecular defects in the insulin signaling pathways are present in VSMCs derived from animal models, diabetic patients, and from healthy individuals in culture conditions mimicking insulin resistance." (PMID 25138792, 2014).